SP1 (Sp1 transcription factor)
Diseases named in the same sentence as SP1 in open-access papers (continued):
Sharing a sentence is not in itself a finding about the gene and the disease.
cancer (continued). "SP1 and ESRRA, are instead associated with anti-cancer compounds which have not been tested in SCI thus far." (PMID 29758010, 2018). "SP1 and SP3 expression level are often greater in cancer cells than in normal cells." (PMID 30386180, 2018). "Although KRT19 regulates EGR1/PTEN/AKT, β-catenin/NUMB/NOTCH, and HER2/ERK/SP1 cascades, we focused on the AKT, GSK3β, ERK, Src, and JNK signaling pathway in this study, as these signaling pathways are crucially involved in cancer progression." (PMID 29747452, 2018). "Transcription factors such as Sp1, NF-κB, TCF, and hypoxia-inducible factor 1α, that are frequently activated by different types of cancer-related signaling pathways, binds to the cis-acting elements located upstream of the PLAUR gene to trigger its elevated expression in cancer." (PMID 29484286, 2018). "Our study has identified a novel role of TIP60 in regulating the function of Sp1 at the TERT promoter by acetylating Sp1 at K639 and we speculate that this may be a feature common to all virus-induced cancers." (PMID 29045464, 2017). "Recently, Sp1 is found to transcriptionally activate MALAT1 expression through targeting the promoter region and the Sp1-MALAT1 axis may play a critical role in cancers." (PMID 28615056, 2017). "Thus, Sp1 and UHFR1 play important roles in the regulation of RIP3 expression and necroptosis in cancer cells." (PMID 28981102, 2017). "The down-regulation of SP1 enhanced the sensitivity to anti-cancer drugs, the cleavage of FAK and the caspase-3 activity in response to anti-cancer drugs in Malme3MR cells." (PMID 28099142, 2017). "We have reported that the anti‐cancer drug ISO downregulates Sp1 translation to block BC cell growth and IHC‐P results show Sp1 is upregulated in BBN‐induced BC tissues, suggesting an oncogenic role of Sp1 in BC." (PMID 28846829, 2017). "In carcinoma cells, a GC-rich NAB2 proximal promoter located within 600 bp upstream of the transcription start site (TSS) has been functionally defined, including several Egr1/Sp1 response elements." (PMID 29152069, 2017). "Using cancer miRNA Transcriptome PCR Array (SureFIND) we first identified miR-23b as one of the most significant negative regulator of Sp1 expression (data not shown)." (PMID 26771806, 2016). "Although there are a few reports indicating that Sp1, Sp3 and Sp4 differentially regulate some genes and coregulate others, the functional roles of Sp3 and Sp4 compared to Sp1 in cancer cells have not been extensively investigated." (PMID 26967243, 2016). "Moreover, the binding of Sp1 to the PTEN core promoter inhibits PTEN expression and results in increased cancer cell migration and invasion." (PMID 26763486, 2016). "In summary, this study indicates that Sp1, Sp3 and Sp4 are NOA genes that are highly expressed in tumor vs. non-tumor tissue and regulate expression of pro-oncogenic factors that contribute to cancer cell growth, survival and migration/invasion." (PMID 26967243, 2016). "We found that both Sp1 and PLD1 were elevated in cancer cell lines compared to HPDE." (PMID 27713167, 2016). "Furthermore, SUMOylation by PIASy can modify Sp1 and suppress the expression of the sirtuin 1 (SIRT1) gene in ovarian and lung cancer cells." (PMID 26703734, 2015). "Sp transcription factors are overexpressed in multiple tumors and cancer cell lines and there is evidence that Sp1 is a negative prognostic factor for patients with several different cancers including HCC." (PMID 26317792, 2015). "To date, there are no reports on Sp1-mediated regulation of the EPAS1 gene, which encodes HIF-2α, in cancer cells." (PMID 26703734, 2015). "Therefore, although the regulatory function of ETS and SP1 by miR-324-5p on HCC invasion was demonstrated in this study, the in-detailed mechanisms of miR-324-5p in cancer ECM degradation and invasiveness need to be further clarified." (PMID 26177288, 2015).
cancer (continued). "The NDR promoters, unlike the NP promoters, were enriched for binding motifs for specific transcription factors such as SP1 and NRF1, typical “housekeeping” transcription factors that normally protect CGI promoters from methylation in both normal and cancer cells." (PMID 25747664, 2015). "Sp1, a member of Sp/KLF (Krüppel-like factor) transcription factors family, which was expressed highly in numerous cancers and important for a variety of physiological processes, including angiogenesis, cell cycle progression, inflammation, and senescence 30–32." (PMID 25639535, 2015). "Sp1 is a member of the Sp/Krüppel-like factor (KLF) family of transcription factors that play a critical role in embryonic and early postnatal development, differentiation, cell cycle regulation and in multiple diseases, including cancer." (PMID 25395235, 2015). "The first genome-scale analysis of transcription factor binding sites in cancer found that binding by transcription factors such as Sp1, NRF1, and YY1 could protect CpG island gene promoters from cancer-specific hypermethylation." (PMID 25994056, 2015). "As EPAS-1 plays an important role in tumor cell survival and proliferation via participating indispensably in SP-1 transcription factor-mediated FBI-1 induction, it could be a novel therapeutical target for cancer intervention." (PMID 25192290, 2014). "In addition, decreased levels of Sp1 in the late stages of cancer increased the expression of FOXO3 and N-cadherin, leading to cancer metastasis." (PMID 24519909, 2014). "Moreover, the expression level of AMACR in common carcinomas is known to be mostly regulated by various transcriptional factors, such as C/EBP family members, Sp1, and ZNF202." (PMID 25473890, 2014). "It has also been reported that zinc depletion induces apoptosis and decreases Sp1, Sp3 and Sp4 in cancer cell lines, and we confirmed that aspirin-induced PARP cleavage and downregulation of Sp1, Sp3 and Sp4 was inhibited in RKO and SW480 cells cotreated with aspirin plus ZnSO4." (PMID 23110215, 2012). "Notably, SP1 binds to the SNHG1 promoter region, enhancing SNHG1 transcriptional activity and forming a positive feedback regulatory loop involving SP1/SNHG1/miR-199a-5p, which further amplifies pro-cancer signaling." (PMID 41234719, 2025). "PPARƔ/Sp1 interactions were also involved in decreased fatty acid synthesis; induction of adipocyte triglyceride lipase (Atgl); induction of acetyl-CoA synthetase (AACS); and decreased follistatin, KDR, angiotensin type 1 receptor (AT1R) and the thromboxane receptor in non-cancer cell lines." (PMID 39858066, 2025). "Therefore, despite the limitations, we assume that the results of our study on DNA methylation of apoptosis-associated genes suggest the possible involvement of five genes (SETDB1, TWIST1, HDAC1, SP1, and GRIA2) in the phenomenon of inverse comorbidity of neurodegenerative diseases and cancers." (PMID 40843670, 2025). "However, a role for SP1-WNT signalling axis in metastatic progression had remained poorly understood, thereby highlighting the importance of our study which has clearly filled this knowledge gap that applies at the pan-cancer level." (PMID 39748426, 2025). "In this regard, it is worth noting that there are inhibitors to known TBX2 co-factors (e.g. HDAC1/2 and Sp1) and upstream regulators (e.g. PI3K/AKT and Wnt/β-catenin) that are already FDA-approved or currently undergoing clinical evaluation for their therapeutic potential in cancer treatment." (PMID 39912718, 2025). "In cancer cell lines, studies have demonstrated that genetic or pharmacological inhibition of MYC in MCF10A basal breast cells results in increased sensitivity to TGFB-stimulated invasion and metastasis, and signaling via Smad3 and ERK/Sp1 mediate TGFB-induced EGFR upregulation." (PMID 41373732, 2025). "Thus, targeting Sp1- and Sp3-mediated FLIP regulation may offer a novel therapeutic strategy for cancers such as prostate cancer." (PMID 40869407, 2025).
cancer (continued). "Furthermore, similar effects were observed for SP1-overexpression induced migratory behaviour in normally non-metastatic cancer cells (HCC1806)." (PMID 39748426, 2025). "Moreover, TFs Sp1 and NRF2 can induce PTGS2 expression in cancer cells." (PMID 38778047, 2024). "Sp1, a particular protein transcription factor, is found to be highly expressed in many tumors, serving as a gene that is not oncogenic but essential for cancer growth." (PMID 39228402, 2024). "Since the miR-29b/Sp1 feedback loop is deregulated in other hematological malignancies, like KIT-driven AML, it is tempting to speculate that G-1 might trigger anti-tumor effects also in these cancers." (PMID 37759449, 2023). "In addition, many studies have shown that SP1, HIF1A, and MYC are often upregulated in cancer." (PMID 37998757, 2023). "However, in our in vitro conditions, cancer cells are not in contact with other hepatic stromal cells also expressing SP1, and complex cell–cell interactions occurring in the tumoral microenvironment are absent." (PMID 36139435, 2022). "Rockwell glycosylation plays an important role in cancer biology and rockwell glycosyltransferase IV (FUT4) is an essential enzyme that catalyzes the synthesis of Lewy’s oligosaccharides and is regulated by the specificity protein 1 (SP1) and heat shock factor protein 1 (HSF1) transcription factors." (PMID 36313365, 2022). "However, inhibitors that specifically target Sp1 and miRNA mediated-Sp1 inhibition in cancer treatment have not been developed." (PMID 33472586, 2021). "SP1 could modulate EMT, the proliferation and invasion of cancer cells by regulating related genes." (PMID 33276722, 2020). "Interestingly, a dramatic increase in Sp1 expression was observed in both TMZ-resistant and cancer stemlike GBM cells in our previous studies, and BA could induce proteasome-dependent degradation of Sp1 by increasing its SUMOylation." (PMID 32326583, 2020). "Interestingly, Sp1 is also known to upregulate MMP2 and MMP9 in cancer cells." (PMID 30845713, 2019). "Our previous observation that AP-1 and Sp1 are activated by TMPRSS4 led us to anticipate that TMPRSS4 may modulate cancer cell survival and that inhibition of TMPRSS4 may be an efficient therapeutic strategy for cancer treatment." (PMID 31292507, 2019). "Therefore, we deduced that Sp1 might recruit DNMT1 to promote DNA methylation in the PDSS2 promoter region, resulting in repressed expression of PDSS2 transcription in cancer cells." (PMID 31783675, 2019). "Moreover, an earlier study showed that Sp1 upregulates MMP2 and MMP9 in cancer cells." (PMID 30845713, 2019). "Here we report that hYSK1 directly interacted with p21WAF1/Cip1, thereby resulting in SP-1-mediated suppression of p16INK4a promoter activity and increased MMP-2 expression under hypoxic condition leading to increased proliferation and migration of cancer cells." (PMID 30646538, 2019). "There was a weak SP1 site (QS = 128) but it came from a carcinoma cell-line not ECs." (PMID 30802244, 2019). "Although the presence of the Sp1 protein in HCC cells explains the majority of TIAM2S expression in these cancer cells, a few cases where TIAM2S expression under low or no expression of Sp1 indicate the possibility of other regulatory mechanisms being involved in controlling TIAM2S expression." (PMID 26763486, 2016). "SP-1 (Specificity Protein 1) is often overexpressed in cancer and may be a negative prognostic factor for the overall survival." (PMID 26405162, 2015).
cancer (continued). "This study suggested that the PP2A/JNK/Sp1/CDK1 cell signaling pathway and autophagy/p21 pathway may be responsible for the G2/M cell cycle arrest and cytotoxicity by treatment with PP2A inhibitors in cancer cells." (PMID 26053095, 2015). "It has been reported that SP1 could cooperate with MYC to activate transcription of the human telomerase reverse transcriptase gene (TERT), which is responsible for maintenance of the length of telomeres and its defects may lead to diseases including cancer." (PMID 26083494, 2015). "However, to date, there are no reports indicating that self-assembly of Sp1 occurs in tumors and contributes to the expression of cancer phenotypes." (PMID 26703734, 2015). "Furthermore we analyzed the effect of miR-149 overexpression in two HCC cell lines, HepG2 and MHCC97H, on the expression of PPM1F and other putative target genes (GIT1, SP1, FOXM1) previously reported by other groups to promote migration and invasion in other cancer cell lines." (PMID 26498692, 2015). "Sp1 is overexpressed in various cancers including GC, but not in normal tissues." (PMID 26695186, 2015). "Also, Sp1 is able to recruit HDAC1 to the promoter of phosphatase and tension homolog deleted on chromosome ten (PTEN), which then inhibits PTEN expression and enhances cancer cell migration and invasion." (PMID 24830600, 2014). "Therefore, Sp1 protein levels are expected to be a negative prognostic factor and a potential therapeutic target for cancer chemotherapy." (PMID 24423061, 2014). "However, regulation of Sp1 protein levels via proteasome-dependent degradation as not been studied as a mechanism for controlling the amount of Sp1 in cancer cells." (PMID 25418289, 2014). "However, regulation of Sp1 levels by proteasome-dependent degradation has not been investigated as a possible mechanism for controlling the amount of Sp1 in cancer cells." (PMID 25418289, 2014). "Thus, Sp1 protein levels are expected to be a negative prognostic factor and potential therapeutic target for cancer chemotherapy." (PMID 22734486, 2012). "However, Sp1 is often found to be overexpressed in cancer, making it a negative prognostic factor." (PMID 37833989, 2023). "As Sp1 and Sp3 are overexpressed in most cancer types, have been characterized as non-oncogene addiction genes, and have been studied as potential biomarkers for recurrent PCa, these key findings highlight the importance of examining the AR, Sp1 and Sp3 signaling axis in PCa." (PMID 35018219, 2022). "Also it was part of a miR-17-92-ZBTB4-Sp transcription factor network that determined the inversely correlated expression of ZBTB4 and Sp1, which were positive and negative prognostic factors, respectively, for survival/relapse-free survival of cancer patients." (PMID 28978185, 2017). "It changes a putative stimulatory protein (Sp1) binding site in the promoter of COX-2 between −766 and −761 bp, but it creates an E2 promoter factor (E2F) binding site, leading to high transcription activity and increased COX-2 expressions which might be involved in the development of cancers." (PMID 24733273, 2014). "While the emCpGs harbour enriched binding sites for their specific emTFs, the non-correlated CpGs shared a binding signatures for SP1, CTCF, NRF1, GABPA, KLF9, and YY1 providing a protective effect against de novo methylation across cancer types." (PMID 35440061, 2022). "The transcription of TERT is regulated by many positive and negative factors, and SP1 and Myc are two common transcription factors that activate TERT expression in cancer cells." (PMID 33239622, 2020). "Cancer studies have shown that when ESR1 is under-expressed, it fails to activate SP1, resulting in decreased expression of downstream genes that regulate a variety of processes including cell cycle regulation, proliferation, and apoptosis." (PMID 31025158, 2019).
cancer (continued). "In contrast, the expression of anti-apoptotic protein XIAP and transcription factor Sp1, which has shown to be suppressed by ISO in human cancer cells, was not affected upon ISO treatment in Cl41 cells." (PMID 24797581, 2014). "To explore a direct role for SP1 in driving WNT pathway activity to promote metastatic features, we further analyzed the SP1 ChIP-seq datasets from metastatic (HCT116) and non-metastatic (MCF7) cancer cells." (PMID 39748426, 2025). "Finally, the study does not explore other potential non-canonical functions of ADAR1 beyond the miR-335-5p/Sp1/GPX4 pathway, leaving gaps in understanding its broader role in cancer biology." (PMID 40852728, 2025). "This suggested that the inhibition of SP1, MYC, and HIF1A should have strong negative impacts on the expression of stem cell- or EM transition-related cellular mechanisms that play important roles in the progression of cancer cells." (PMID 39590335, 2024). "Our studies also identified agents that prevent ferroptotic death in cancer cells and neurons that would not be good candidates for cancer treatment (e.g., HIF PHD inhibitors, transglutaminase inhibitors, and the gene selective Sp1 inhibitor Mithramycin)." (PMID 30783618, 2019). "Thus, proper manipulation of SP1, HIF-1, and MYC by appropriate agents could have a strong negative impact on cancer development." (PMID 37998757, 2023). "However, the combined siRNA-mediated knockdown of Klf4 and Sp3 resulted in consistent up-regulation of Notch1 expression in both HKCs and cancer cells (HeLa and SCC13 cells), with the concomitant knock-down of Sp1 having no additional effects (C and data not shown)." (PMID 20442780, 2010).